AGT (angiotensinogen)
Diseases named in the same sentence as AGT in open-access papers (continued):
Sharing a sentence is not in itself a finding about the gene and the disease.
Hypertension (continued). "Polymorphisms in the angiotensinogen gene (M235T and A-20C) have been associated with hypertension, faster progression to ESRD, susceptibility to nephropathy in patients with type I diabetes mellitus, and progression of renal dysfunction in adults and children with IgA nephropathy." (PMID 19274077, 2009). "The M235T polymorphism in the AGT gene has been related to an increased risk of hypertension." (PMID 18575631, 2008). "Biological and positional candidate genes, like the angiotensinogen (AGT) gene, are more likely to be associated with differences in the pathophysiology of BP, differential risk of developing hypertension, and variability in BP response to antihypertensives in the population at large." (PMID 17854487, 2007). "The effect of a combination of ACE and AGT gene polymorphisms on hypertension was also examined." (PMID 15642127, 2005). "However, the M235T TT genotype of AGT gene was detected to confer a significantly decreased risk for the prevalence of hypertension in women from this particular population." (PMID 15642127, 2005). "Therefore, the finding that the AGT TT genotype associated with a decreased risk for essential hypertension is likely to be true for this particular German population." (PMID 15642127, 2005). "Two polymorphisms on the angiotensinogen gene (rs699 and promoter region variants) and one on the angiotensin I converting enzyme gene (an insertion/deletion polymorphism) have been researched as possible links to the physiological pathways behind HC-induced hypertension." (PMID 41323407, 2025). "This broader approach may unveil rare functional AGT genetic variants linked to hypertension." (PMID 38541014, 2024). "In the same line of evidence, adipocyte AGT deficiency prevented high fat-induced elevations in plasma Ang II concentrations and systolic blood pressure, suggesting that adipose tissue is a major source of Ang II in developing obesity, hypertension, and insulin resistance." (PMID 35682723, 2022). "AGT M235T is one of the genetic polymorphisms that may influence left ventricular mass due to its pivotal role in the regulation of plasma angiotensinogen level as well as hypertension pathophysiology in Asian populations." (PMID 33681303, 2021). "It has been well documented that angiotensinogen plays a fundamental role in fine-tuning the tightly controlled activity of the renin-angiotensin system and ultimately blood pressure itself, and has thus been associated with various hypertensive disorders and cardiovascular disease." (PMID 34424335, 2021). "Other factors (PPARGC1, AGT) and drugs (losartan) related to vasoconstriction suggest that alterations in blood pressure, such as those seen in hypertension, might underlie CSD effects on bECs." (PMID 32413560, 2020). "Therefore, our study aimed to establish the role of ACE and AGT gene polymorphisms in the mechanisms behind the development of oxidative stress in patients with concomitant chronic obstructive pulmonary disease and hypertension." (PMID 32025262, 2019). "Likewise, AGT overexpression is associated with hypertension and renal tubular damage." (PMID 31803758, 2019). "Also, an AGT mutation where Leu10 is replaced by a Phe, resulting in a mere 2-fold increase in the cleavage efficiency of the mutant by renin, is associated with the development of preeclampsia, a life-threatening hypertensive disorder during pregnancy." (PMID 30563843, 2019). "As a consequence, the use of angiotensinogen ASO for the treatment of hypertension has currently been abandoned." (PMID 39808369, 2025). "Clinical studies have demonstrated the beneficial effect of reducing circulating angiotensinogen, a precursor of angiotensin, to lower blood pressure in patients with hypertension." (PMID 40045320, 2025).
Hypertension (continued). "Earlier studies on hypertension have focused on this subsequent cleavage of angiotensin-1 by the angiotensin-converting enzyme ACE, with the role of angiotensinogen being initially relegated to that of a passive substrate." (PMID 40699774, 2025). "The deduced modulatory role of the 18–138 disulphide is in keeping with repeated reports that episodic hypertension can be triggered by oxidative stress, which favours a transition of angiotensinogen to its more active bridged form." (PMID 40699774, 2025). "In the Multi-Ethnic Study of Atherosclerosis, also known as MESA, average level of angiotensinogen and prevalence of hypertension differed significantly among racial/ethnic groups (White, Chinese, Black and Hispanic)." (PMID 40356318, 2025). "This index case, however, completes a chain of evidence linking the onset of pre-eclamptic hypertension to the observed change in the cleavage kinetics of angiotensinogen following its oxidative exposure in the placenta." (PMID 40699774, 2025). "For example, studies have shown that targeting angiotensinogen via siRNA reduces blood pressure and mitigates cardiac hypertrophy in animal models, highlighting the potential of RNA-based approaches to manage hypertension." (PMID 40182424, 2025). "The risk gene AGT, a key component of the renin-angiotensin system (RAS), highlights the intersection of systemic hypertension and neurodegeneration." (PMID 40355913, 2025). "Animal studies have provided detailed information on the mechanism of action and the efficacy of angiotensinogen siRNA in the treatment of hypertension." (PMID 41156232, 2025). "The elevated concentrations of AGT in the circulatory system induce an upsurge in the synthesis of angiotensin II, and thereby culminating the manifestation of hypertension." (PMID 40642296, 2025). "Recently, zilebesiran, a subcutaneously administered siRNA-targeting liver-expressed angiotensinogen, was developed to treat hypertension." (PMID 38672564, 2024). "Others are also emerging on the arterial hypertension front with the development of aldosterone synthase inhibition and zilebesiran, the first small interfering RNA (siRNA) designed to reduce angiotensinogen mRNA in the hepatocytes." (PMID 38673568, 2024). "This review evaluates new RNAi therapeutic approaches for SAH targeting hepatic AGT, highlighting existing knowledge gaps and identifying opportunities for future research on hypertension and emerging gene silencing therapies." (PMID 39852196, 2024). "It is crucial to emphasize that, as far as our knowledge extends, no prior studies in Jordan have undertaken the task of exploring the genotyping of the AGT gene (T704C) among individuals with hypertension." (PMID 38541014, 2024). "We investigated the potential of RNA interference (RNAi) therapies targeting hepatic angiotensinogen (AGT) for hypertension management." (PMID 39852196, 2024). "Zilebesiran (ALN-AGT01), which targets angiotensinogen (AGT), is being developed for hypertension treatment." (PMID 39609384, 2024). "Offspring hypertension in this model is linked to Ang II-dependent hypertension, with augmented renal ACE activity and AGT and ACE mRNA expression in adult progeny." (PMID 38542273, 2024). "Higher levels of angiotensinogen correlate strongly with the incidence of obesity and hypertension, especially in women." (PMID 39683432, 2024). "Animals with transgenic hap-I chromatin showed stronger binding to glucocorticoid receptor transcription factors and hepatocyte nuclear factor 3β than hap-II animals, resulting in higher plasma AGT concentrations and the development of hypertension." (PMID 39852196, 2024). "Another phase 2 study with 26 participants with treatment-resistant hypertension receiving 2–3 antihypertensive medications showed a significant 67% AGT reduction by day 57 in those receiving 80 mg weekly IONIS-AGT-LRx doses (nine doses in total)." (PMID 39852196, 2024).
Hypertension (continued). "All benefits found with present RAASis in regard to treatment of hypertension, kidney disease, heart failure, atherosclerosis and metabolic disorders are expected to be also present when suppressing AGT." (PMID 38612843, 2024). "This study provides valuable insights into RNA-based therapies for hypertension, highlights the importance of AGT in BP regulation, and discusses the efficacy of different therapeutic approaches that target hepatic AGT." (PMID 39852196, 2024). "When proinflammatory cytokines are activated, hypertension is induced and related to increased levels of AGT." (PMID 38786142, 2024). "Although adipocyte-specific angiotensinogen production has been reported to be a major source of circulating AngII, the contribution of adipose AngII to obesity-related hypertension is still unclear." (PMID 38186879, 2024). "Proteins with high disease scores (76–100% confidence) for both hypertension and chronic kidney disease included angiotensinogen (AGT), albumin (ALB), apolipoprotein L1 (APOL1), and uromodulin (UMOD)." (PMID 38402394, 2024). "In a meta-analysis, it was reported that only a limited number of studies have evaluated the involvement of AGT gene with the development of hypertension in African populations." (PMID 38706806, 2024). "Clinical trials targeting angiotensinogen in the treatment of hypertension and heart failure are ongoing." (PMID 39683432, 2024). "In the present study, we demonstrated that male mice with OW exhibited increased urinary AGT before the development of hypertension and kidney injury." (PMID 38203807, 2024). "Conversely, central knockdown of ERα negates the protective effect on Ang II-induced hypertension, resulting in a significant increase in AT1, ACE1 and renin, along with a decrease in angiotensinogen." (PMID 39655343, 2024). "Proteins angiotensinogen (AGT), albumin (ALB), APOL1, and uromodulin (UMOD) were associated with CKD and hypertension with high disease scores of 5.0 (100% confidence), 4.0 (80%), 3.9 (78%), and 3.8 (76%), respectively." (PMID 38402394, 2024). "Resistin is significantly increased during obesity, plays a role in insulin resistance, and induces hypertension by inducing angiotensinogen." (PMID 38784171, 2024). "The candidacy of the AGT gene in hypertension was first described by Jeunemaitre and coworkers in Utah and Paris family." (PMID 37201134, 2023). "Two ongoing clinical trials are specifically evaluating a subcutaneous RNAi therapeutic targeting liver-expressed angiotensinogen for the treatment of hypertension." (PMID 36672629, 2023). "Intramedullary injection of butyrate can dramatically lower Ang II-induced hypertension in hypertensive rats by inhibiting the release of renin and angiotensinogen." (PMID 38029244, 2023). "Urinary angiotensinogen (uAGT) is a novel biomarker of the activation of the renin–angiotensin system (RAAS) in patients with ADPKD, and it is associated with hypertension, progressive kidney damage, proteinuria, and cardiovascular morbidity and mortality." (PMID 37241147, 2023). "Previous studies have found potential interactions between ACE, AGT, angiotensin II type 1 receptor (AGTR1), and α adducin (ADD1) variants and correlations between them and clinical endpoints in individuals with hypertension." (PMID 37091860, 2023). "More recently, adipose-tissue specific knockout of Bone Morphogenetic Protein 4 (BMP4) in apolipoprotein E (ApoE) knockout mice gave rise to high levels of angiotensinogen, angiotensin II, and ROS, resulting in hypertension development." (PMID 37190105, 2023). "The manipulation of RAS has generated a model of spontaneous hypertension in which crossing a transgenic mouse overexpressing human Renin (hRen) and a mouse overexpressing human Angiotensinogen." (PMID 37539342, 2023). "Among all the components, genetic polymorphism in angiotensinogen (AGT) and angiotensin-1-converting enzyme (ACE) are the most reliable candidate risk for hypertension given consistent findings." (PMID 37201134, 2023).
Hypertension (continued). "In this context, ALN-AGT01 is an investigational RNAi subcutaneously administered angiotensinogen-targeted (AGT) drug under development for the treatment of hypertension in low pharmaceutical adherence populations." (PMID 36672629, 2023). "Our study went one step further to show that perinatal use of taurine can protect offspring from hypertension along with restoring the expression of renin, AGT, ACE, and AT1R induced by maternal CKD." (PMID 38136178, 2023). "Recent studies showed that urinary AGT/Cr was strongly associated with advanced CKD stages, htTKV, and hypertension." (PMID 37241147, 2023). "Renin, a hormone secreted by the kidneys, acts on its substrate to catalyze the transformation of angiotensinogen into angiotensin I. Angiotensin I is known to be a powerful vasoconstrictor that contributes to the development of hypertension." (PMID 37869088, 2023). "We found that AGTR1 A1166C (p = 0.01), AGT M235T (p = 0.01), AGT T174M (p = 0.02), hypertension (p = 0.03), smoking (p = 0.02), and family history of atherothrombotic disease (p = 0.04) were independently associated." (PMID 38025202, 2023). "While some evidence from animal studies have found FoxO1 to be protective to the heart, others have reported that increasing FoxO1 expression increase angiotensinogen and angiotensin II levels, which are important in the pathogenesis of hypertension." (PMID 37089429, 2023). "Although the dogs received medication (ACE-i) for the control of hypertension, serum AGT concentrations were still high after treatment." (PMID 35203200, 2022). "When estrogen (ethinyl estradiol) was administered to a rat model for 12 weeks, hypertension occurred and levels of angiotensinogen and angiotensin II increased." (PMID 34991554, 2022). "One of the most important mechanisms whereby IFN-γ triggers hypertension is that IFN-γ can increase the expression of angiotensinogen of rat renal proximal tubule cells in a JAK2/STAT3-dependent manner, which consequently increases blood volume." (PMID 36703963, 2022). "AGT is an inactive precursor of potent vasoactivity and the salt-retention hormone angiotensin II, and an elevated level of it is the primary precursor in the pathogenesis of hypertension." (PMID 35600357, 2022). "Both angiotensinogen-specific antisense oligonucleotides and small interfering RNA (siRNA) lowered blood pressure in rat models of hypertension." (PMID 36519165, 2022). "Heterogeneous nuclear ribonucleoprotein can mediate insulin-driven inhibition of renal angiotensinogen gene expression and prevent hypertension and kidney injury in diabetic mice." (PMID 36140769, 2022). "Genetic variations in the AGT gene have been related to hypertension, endometrial cancer, pre‐eclampsia and spontaneous abortion." (PMID 33960101, 2022). "As mentioned, renal proximal tubular AGT regulation has been shown to play crucial roles in the development of kidney injury in hypertension." (PMID 35887028, 2022). "Although this approach is still in its infancy, initial studies in SHR suggest that partial deletion (40%) of the hepatic AGT gene is sufficient to prevent the development of hypertension in this model." (PMID 35904033, 2022). "Although kidney-specific AGT overexpression in transgenic mice indeed resulted in hypertension, we now know in section II.C, that the role of locally synthesized AGT in the kidney is marginal, if not absent." (PMID 35710133, 2022). "Hypomethylation of the angiotensinogen gene (AGT) promoter can activate AGT expression in adipose-induced hypertension." (PMID 35740428, 2022). "Next, the renal RAS in hypertension, kidney disease, and metabolic disease is discussed, critically addressing the role of urinary AGT as a biomarker reflecting renal RAS activity." (PMID 35710133, 2022). "Previous findings from animal studies have shown the impact of salt intake, hypertension, and proinflammatory cytokines on methylation and expression of the AGT and CYP11B2 gene." (PMID 36457109, 2022).
Hypertension (continued). "Accordingly, an activated immune system can serve as an important mediator of augmentation of proximal tubular AGT in Ang II-dependent hypertension." (PMID 35887028, 2022). "To focus on the role of PVAT metabolism in hypertension development, we chose AGT for further study." (PMID 36457800, 2022). "In conclusion, this study demonstrated that stimulated IL-6 production in activated macrophages contributes to intrarenal AGT augmentation in the early stages of Ang II-dependent hypertension, which leads to the development of kidney injury." (PMID 35887028, 2022). "An angiotensinogen/melatonin ratio is suggested as an early biomarker for identification of gestational diabetes or hypertension." (PMID 35309508, 2022). "A recent cross-sectional study showed that urinary angiotensinogen/creatinine ratio was correlated with high blood pressure and proteinuria in preeclampsia." (PMID 35309508, 2022). "Renin is another target to control hypertension because this enzyme generates angiotensin I from angiotensinogen." (PMID 34828976, 2021). "In hypertension induced by angiotensin II (AngII) administration with high salt (HS) intake, intrarenal angiotensinogen (AGT) and tumor necrosis factor‐alpha (TNF‐α) levels increase." (PMID 34427402, 2021). "Angiotensinogen itself mainly inhabits vasoconstrictive properties and is known to affect the development of vascular diseases such as hypertension and atherosclerosis." (PMID 34580391, 2021). "Gene polymorphisms linked to the renin–angiotensin (AGT)–aldosterone system (RAAS) were broadly inspected in patients with diabetic nephropathy (DN) and hypertension." (PMID 33668947, 2021). "The renin–angiotensin–aldosterone system is involved in the development of severe hypertension, and some polymorphisms of the angiotensin-converting enzymes (ACE) or angiotensinogen encoding genes are associated with early onset hypertension." (PMID 33430236, 2021). "AGT M235T genotype, duration of hypertension, body mass index, and ejection fraction statistically affected the left ventricular mass index, which was significantly greater in TT compared to MT carriers after adjusting for confounding factors." (PMID 33681303, 2021). "What can be concluded with confidence is that the recognition of the structurally well-defined helix H binding-pocket in angiotensinogen now provides a basis for the design of new agents to attenuate angiotensin release and thus alleviate hypertension." (PMID 33816576, 2021). "The knockout of AGT, PRR, or ATRs specifically into the brain blocks hypertension, while overexpression of genes enhancing ANGII production in the brain leads to hypertension in rodents." (PMID 34827650, 2021). "Sprague-Dawley female rats transgenic for the human angiotensinogen gene (hAogen) develop proteinuria and hypertension when mated with male rats transgenic with the human renin gene." (PMID 33969702, 2021). "In our analyses, the renin-angiotensin system, metabolism of angiotensinogen to angiotensin, and peptide hormone metabolism pathways were found to be shared by both hypertension and COVID-19." (PMID 34067609, 2021). "Insulin is able to reduce hypertension and oxidative stress, and at the same time, to inhibit angiotensinogen expression and the NRF2 pathway." (PMID 34829520, 2021). "Mervaala and colleagues documented that rodents with over-expressed human renin and angiotensinogen genes have raised XO activity with endothelial dysfunction and hypertension." (PMID 33639960, 2021). "Urinary angiotensinogen (AGT) is an index of intrarenal renin-angiotensin system (RAS) status with hypertension and progression to CKD being prominent features of (untreated) ADPKD." (PMID 34206927, 2021). "Yet, when crossing female human AGT transgenic mice with male human renin transgenic mice, the pregnant mice did develop a pre-eclamptic phenotype, characterized by hypertension, elevated sFlt-1 levels and proteinuria." (PMID 34299027, 2021).